NUTM2A (NUT family member 2A)
Synonyms: FAM22A
Tractability: No criterion of Open Targets' tractability assessment is met for any kind of drug.
Gene: Protein-coding gene on chromosome 10 (87,225,448 to 87,236,908, forward strand). Ensembl gene ENSG00000184923.
Subcellular location (Human Protein Atlas): Nuclear bodies
Genetic constraint (gnomAD): Loss-of-function variants: 1 observed, 3.97 expected, observed/expected ratio (o/e) 0.25, 90% interval 0.088 to 1.18. That is too few expected variants to judge how well the gene tolerates losing a copy. Missense variants: 14 observed, 151.28 expected, observed/expected ratio (o/e) 0.0925, 90% interval 0.06 to 0.14. Synonymous variants: 3 observed, 61.87 expected, observed/expected ratio (o/e) 0.0485, 90% interval 0.021 to 0.12.
Homologues: Orthologues: macaque NUTM2A (76% identical), rat Nutm2 (34% identical), mouse Nutm2 (33% identical). Paralogues in human: NUTM2B (98% identical), NUTM2E (98% identical), NUTM2D (90% identical), NUTM2F (72% identical), NUTM2G (71% identical), NUTM1 (41% identical).
Diseases named in the same sentence as NUTM2A in open-access papers:
NUTM2A is named in the same sentence as 14 diseases in open-access papers, as found by Europe PMC text mining. Sharing a sentence is not in itself a finding about the gene and the disease. The quoted sentences say what the papers report.
endometrial stromal sarcomas (8 papers, 2013 to 2025). "NUTM2A (NUT family member 2A), also known as FAM22A, reported that YWHAE-NUTM2A fusion transcript is associated with aggressive endometrial stromal sarcomas." (PMID 35038288, 2022). "YWHAE encodes a protein of the 14-3-3 family, and has been found fused to FAM22, or NUTM2A/B/E, in endometrial stromal sarcoma and clear cell sarcoma of the kidney." (PMID 32825119, 2020).
sarcoma (3 papers, 2019 to 2025). A usually aggressive malignant neoplasm of the soft tissue or bone. "Specifically, NUTM2A/B represent frequent fusion partners in subsets of high‐grade endometrial stromal sarcoma (ESS), clear cell sarcoma of the kidney, CIC‐rearranged sarcomas, and emerging primitive undifferentiated pediatric sarcomas." (PMID 40944358, 2025). "Moreover, CIC fusion to non-DUX4 genes such as FOXO4, NUTM1, and NUTM2A seems to lead to histology and features similar to those with CIC-DUX4, although CIC-LEUTX sarcomas are related to CD31 and ETS-related gene expression." (PMID 31676869, 2019).
acute leukemia (1 paper, 2021). A clonal (malignant) hematopoietic disorder with an acute onset, affecting the bone marrow and the peripheral blood. "Through this approach, we have discovered three novel KMT2A translocation partners in childhood acute leukemia—genes encoding tyrosine kinase BTK, ubiquitin-protein ligase PRPF19, and NUTM2A—gene of poorly known function." (PMID 34440129, 2021).
lung tumor (1 paper, 2025). "This study introduces a novel salivary and lung tumor entity driven by NFATC2::NUTM2A/B fusions and displaying myoepithelial‐like morphology but imperfect myoepithelial immunophenotype." (PMID 40944358, 2025). "This small series introduces a histologically distinct novel salivary gland and lung tumor entity driven by NFATC2::NUTM2A/B fusions and displaying variable myoepithelial‐like morphology but an imperfect myoepithelial immunophenotype." (PMID 40944358, 2025). "Original diagnoses and immunohistochemical findings in NFATC2::NUTM2A/B fusion salivary gland and lung tumors." (PMID 40944358, 2025).
metastatic tumour (1 paper, 2023). "Driver gene aberrations occurring exclusively in CSF cfDNA and not shared with primary/metastatic tumour or plasma cfDNA (where sequenced) were found in genes involved in histone modification (KAT6B, KMT2D, NUTM2A) and microtubule formation (PDE4DIP)." (PMID 37973922, 2023).
nut midline carcinoma (1 paper, 2021). A rare, highly aggressive and lethal carcinoma that affects children and young adults. "FAM22A/B was renamed NUTM2A/B due to its sequence homology with NUT (NUTM1), which is notable in NUT midline carcinoma." (PMID 33099834, 2021).
tumor (6 papers, 2017 to 2025). "Despite the wide implementation of different next‐generation sequencing tools in surgical pathology and in research studies, neoplasms carrying NFATC2::NUTM2A/B fusions have not been reported before, underlining the rarity of these fusions in general." (PMID 40944358, 2025). "Also, two tumors with morphologic feature of LG‐ESS have had YWHAE rearrangements: a YWHAE/NUTM2A fusion was identified in a tumor confined within the endometrium, whereas deletion of a 3′ probe for YWHAE was shown in an LG‐ESS and in its recurrence in a case showing progression from LG‐ to HG‐ESS." (PMID 33099834, 2021). "We describe four myoepithelial‐like neoplasms of salivary (two) and pulmonary (two) origin, carrying recurrent NFATC2 fusions involving NUTM2B (three) and NUTM2A (one) as fusion partners." (PMID 40944358, 2025). "NUTM2A − AS1, NUTM2B − AS1, SNHG3, and THUMPD3 − AS1 were found to be highly expressed in tumor samples." (PMID 35615532, 2022). "The identification so far of four chimeric transcripts in HG‐ESS—YWHAE/NUTM2A/B, ZC3H7B/BCOR, EPC1/SUZ12, and EPC1/BCOR‐is evidence of genetic heterogeneity also within this tumor subgroup." (PMID 33099834, 2021). "In summary, we presented four cases (two pulmonary and two salivary) of a distinctive low‐grade neoplasm characterized by bland histology, myoepithelial‐like morphology but with an imperfect myoepithelial immunophenotype, recurrent NFATC2::NUTM2A/B fusions, and likely an indolent clinical behavior." (PMID 40944358, 2025). "Finally, NUTM2A − AS1, NUTM2B − AS1, SNHG3, and THUMPD3 − AS1 were identified to be highly expressed in tumor samples and were negatively correlated with prognosis." (PMID 35615532, 2022). "However, insufficient frequency of YWHAE, NUTM2A, and NUTM2B gene rearrangement and absence of mutation in both the c-kit and PDGFRA genes suggested that this tumor should be categorized as epithelioid leiomyosarcoma." (PMID 28288693, 2017).
NUTM2A also shares sentences with these, for which no sentence is quoted: ovarian carcinoma (2 papers); cancer (1); clear cell sarcoma of the kidney (1); CNS tumors (1); Ewing sarcoma (1); myoepithelial neoplasms (1); T-cell ALL (1).